OCLN (occludin)
Diseases named in the same sentence as OCLN in open-access papers (continued):
Sharing a sentence is not in itself a finding about the gene and the disease.
colitis (continued). "Compared to the control group, the expression levels of ZO-1, Claudin-1, and Occludin were markedly decreased in the colon tissues of DSS-induced colitis mice, but QUE treatment significantly enhanced the expression of these TJ proteins." (PMID 39458282, 2024). "In this study, we revealed the protective effects of FGR against DSS-induced colitis via the regulation of expression of tight junction proteins, such as ZO-1, occludin, and claudin-2, and improvement of intestinal barrier dysfunction." (PMID 36829894, 2023). "In colon tissue, the gene expressions of Claudin-1, Occludin and ZO-1 proteins were considerably suppressed in colitis mice but markedly increased in the P10 group." (PMID 37761037, 2023). "The effect of specific HDAC 8 inhibitors has recently been investigated in a murine model of colitis showing barrier-improving effects via upregulation of occludin." (PMID 37375664, 2023). "Colonic biopsies from patients with colitis have been found to express reduced levels of epithelial tight junction proteins such as occludin, claudin-1, -3, -4, and -7, tricellulin, and JAMs." (PMID 37049744, 2023). "In the present study, the inosine intervention dramatically up-regulated the expressions of ZO-1, occludin, and claudin-1 in mice with colitis, which partly explained the alleviative efficacy of inosine on the intestinal barrier functions in mice with colitis." (PMID 37762155, 2023). "As defective tight junction (TJ) integrity is a key pathology of colitis, in our following experiments, two main TJ components of intestinal barrier, occludin and Cldn4, were detected." (PMID 36776831, 2023). "Fp-EVs upregulated the protein expression of zona occludens (ZO)-1 and Occludin and increased the ratio of Tregs in the colon tissue of colitis mice." (PMID 37968625, 2023). "The level of TJ proteins was further examined through immunoblotting, and the results showed that Occludin, Claudin1, and Claudin3) were reduced and Claudin2 was up-regulated within the CR-mediated colitis mice, and this was reversed with GBE treatment." (PMID 37111225, 2023). "Vitamin D-treated IECs showed increased TEER, with upregulation of ZO-1, occludin, and several claudins, while VDR-deleted mice showed increased colonic permeability and susceptibility to DSS-induced colitis." (PMID 36678175, 2023). "SNAI1 has been demonstrated to induce ZEB1 expression and is a potential repressor of E-cadherin and several tight junctions (CLDN1, OCLN, ZO-1) in IECs thereby promoting intestinal barrier dysfunction upon colitis and tumorigenesis in mice." (PMID 37174625, 2023). "The protein expressions of ZO-1, E-cadherin, and occludin were decreased in DSS-induced colitis mice, whereas PHI (25, 50, and 100 mg/kg) or MES (100 mg/kg) treatment observably increased the expressions of TJs (P < 0.05)." (PMID 36768559, 2023). "Immunofluorescence and immunoblot analysis confirmed that the DNBS challenge resulted in a significant reduction in ZO-1 and occludin expression, indicating a severe disruption of the gut barrier integrity in colitis." (PMID 38203336, 2023). "A study has shown that Atractylenolide-1 was able to improve mucoprotein MUC2 and enhance the expression of tight junction proteins ZO-1 and Occludin in mice with colitis." (PMID 37237988, 2023). "The colitis group showed lower expression of the junction protein occludin compared to the Sham group (0.18±0.08 vs 1.09±0.16, respectively, P<0.05)." (PMID 37909497, 2023). "Peripheral membrane proteins (ZO-1), transmembrane proteins (occludin and claudins), and intracellular regulatory molecules are representative tight-ion proteins and TJ damage can occur at the outbreak of colitis." (PMID 37891901, 2023). "We found that the mRNA levels of ZO-1 and occludin were significantly decreased in DSS-induced colitis samples but dramatically increased after Cl-amidine treatment similar to the levels in naïve controls." (PMID 37143672, 2023).
colitis (continued). "Gut barrier integrity maintained by tight junction proteins like ZO-1 and occludin is another sign of colitis severity." (PMID 37143672, 2023). "Comparison with the normal control group indicated that the DSS control group showed a reduction in the levels of claudin-4 and occludin within the colon of mice with colitis, and oral treatment with LAB partially reversed this decrease." (PMID 36187993, 2022). "Given the colitis at 5 weeks, we immunohistochemically examined the expression of epithelium tight junction proteins, zonula occludens (ZO-1) and occludin." (PMID 36456739, 2022). "DEX induced low expression of ZO-1 and occludin in colitis mice and was expressed more in RU486 injected mice." (PMID 36032134, 2022). "The peptides from mucosal protein were investigated to induce the extent of the mucosal barrier as well as pathological features in DSS-induced colitis mice, where the ZO-1 and occludin proteins were enhanced compared with that of DSS group." (PMID 35406093, 2022). "Both the abundance of Lactobacillus and the levels of ZO-1 and Occludin were increased by LBGH in DSS-induced colitis mice, which meant LBGH was beneficial for the intestinal tight junctions." (PMID 36033869, 2022). "In the DSS-induced colitis model, tegoprazan reduced intestinal permeability and upregulated the expression of tight junction proteins Zo-1 and Occludin." (PMID 35693794, 2022). "Propanoic acid increased expression of the tight junction proteins zonula occludens-1 and occludin on the intestinal epithelial barrier in Parkinson’s disease patients and decreased inflammation in a colitis model." (PMID 35252022, 2022). "before modeling markedly mitigated colitis as well as intestinal mucosal damage and apoptosis of colonic epithelial cells by regulating the expression of occludin, caspase-8, and COX-2." (PMID 36160392, 2022). "DSS-induced colitis downregulated occludin expression, while the administration of SPA3074 showed significantly higher occludin expression levels, indicating that administration of SPA3074 suppressed DSS-induced occludin loss." (PMID 36558966, 2022). "In the current work, expression of protein analysis showed that compared with the DSS group, PWE administration increased the expressions of ZO-1 and the occludin protein in colon tissues of DSS-treated colitis mice in a dose-dependent manner." (PMID 35630568, 2022). "In order to explore the effect of yeasts on intestinal barrier function in mice with colitis, the relative expression levels of Claudin–1, Occludin and ZO–1 proteins were determined." (PMID 35627006, 2022). "Correspondingly, Western blot analysis showed that the TJ proteins of E-cadherin, β-catenin, and occludin were enhanced under SM934 treatment compared with TNBS-induced colitis mice in colon tissues." (PMID 36120344, 2022). "Since our previous study revealed that probiotics played a crucial role in protecting the intestinal barrier, we also detected the expression of several tight junction proteins (JAM-1, ZO-1, and Occludin) in the colon tissues from colitis mice." (PMID 35782138, 2022). "In the development of colitis, the expression of tight junction proteins, such as ZO-1, occludin, and claudin-1, is negatively correlated with increased intestinal barrier permeability." (PMID 36590200, 2022). "Our results showed that BEY treatment has significant roles in maintaining the intestinal barrier integrity and preventing colitis, as evidenced by the increased levels of occludin and negative regulation of inflammatory markers in colitis mice." (PMID 35565934, 2022). "The ZO-1, claudin-1 and JAM-1 proteins expressions in intestinal tissues of DSS-induced colitis mice significantly decreased, while occludin protein only showed a decreasing trend." (PMID 35659178, 2022). "Administration of LcS ameliorated the severity of DSS-induced colitis and enhanced intestinal integrity via induction of mucin-2 and occludin expression in colons." (PMID 35529468, 2022).
colitis (continued). "A previous study showed that ginger enhanced the expression of ZO-1 and occludin in the TJ of colonic mucosa in mice with colitis." (PMID 35071260, 2021). "In this study, the expression of NLRP3, ASC, and Cleaved caspase-1 was increased while the expression of CLDN1, OCLN, and ZO-1 was decreased in colon tissues of colitis mice, which were reversed by YST to near normal levels." (PMID 34055024, 2021). "A study demonstrate that the effects induced by DSS fed colitis mice are alleviated by the diet rich in resveratrol and restoration of TJ proteins like ZO-2, occludin, JAM-A, claudins 3,4 and 7 was evident." (PMID 34630140, 2021). "The pharmacological activation of AMPK with FA5 determined a normalization of occludin expression in colonic tissues from rats with colitis." (PMID 34199160, 2021). "VIP protects the distribution and levels of junction proteins (for example, ZO-1, occludin, claudin-3, and claudin-4) against colitis by inhibiting MLCK or PKCε." (PMID 34552687, 2021). "Occludin was reported to be downregulated in colitis and, consistently, in our study its expression was reduced in the DSS group." (PMID 33803793, 2021). "We found that ZO-1 and occludin expression was markedly decreased in PBLDIEC−/− mice compared with WT mice in DSS-induced colitis." (PMID 34059646, 2021). "Of note, the pharmacological activation of AMPK with FA5 exerted a restorative effect on tight junctions in rats with DNBS colitis, showing an ameliorative effect mainly on occludin expression." (PMID 34199160, 2021). "This study demonstrated the protective effects of EDT on DSS-induced colitis and showed that the Shh pathway can upregulate expression of the TJ proteins ZO-1 and occludin, reducing colitis-induced epithelial barrier damage." (PMID 34348563, 2021). "Lactobacillus rhamnosus MTCC-5897 administration before DSS-colitis induction improved intestinal barrier integrity involving transcriptional modulations of TJ genes (ZO-1, OCLN, CLDN-1)." (PMID 34778332, 2021). "In both, Caco-2 monolayers and colitis mice model, Met administration provided protection against the decreased expression of occludin and ZO-1 as well as increased bacterial translocation." (PMID 34616233, 2021). "In the Il10−/− spontaneous colitis model, A. pulmonis colonization significantly downregulated gene expression of several intestinal barrier molecules including Muc2, ZO-1, and Occludin." (PMID 34814945, 2021). "Consistent with the results of TEM, the immunofluorescence analysis in ALS-fed colitis mice revealed an increase in the expression of the tight junction proteins, zonula occludens-1 (ZO-1) and occludin." (PMID 34836184, 2021). "Using colon tissues from both UC patients and colitis mouse models, IL-1β-induced upregulation of miR-200c-3p decreased levels of occludin, which negatively impacted barrier function." (PMID 34943865, 2021). "In this study, it was found that BL increased the expression of Claudin-1, Occludin, and ZO-1 in the intestines of colitis mice." (PMID 33954162, 2021). "We used qRT-PCR and Western blotting assays and demonstrated that SA reduced the activation of the NLRP3 inflammasome and attenuated intestinal permeability by enhancing the expression of ZO-1, occludin, and claudin-1 in colitis mice." (PMID 33312339, 2020). "Impaired occludin, which disrupts the epithelial barrier integrity, was observed in both human UC and mouse model of colitis induced by dextran sodium sulfate (DSS)." (PMID 33381598, 2020). "Sinapic acid treatment also increased the protein levels of claudin-1, occludin, and ZO-1 in the colons of the colitis mice (p < 0.05)." (PMID 33312339, 2020). "Taken together, these findings suggest that C. muridarum upregulates IL-22 and occludin in mice with DSS-induced colitis." (PMID 33381598, 2020). "The in vivo experiment in this study showed that PRCC-1301 EVs recovered the expression and distribution of TJ proteins, ZO-1, claudin-1, and occludin in DSS-induced colitis." (PMID 33233771, 2020).
colitis (continued). "Immunofluorescence assay showed that triptolide treatment significantly upregulated the level of claudin-1 and occludin in DSS-induced colitis." (PMID 33240279, 2020). "We found that occludin, ZO-1, and claudin-1 expression levels in the colon were significantly reduced in colitis mice, and especially claudin-1." (PMID 32855978, 2020). "In DSS-induced colitis mice, both the mRNA and protein levels of occludin, ZO-1, and claudin-1 were found to be decreased in the colon tissue." (PMID 33312339, 2020). "We also investigated the protective effect of PRCC-1301 EVs against DSS-induced disruption of TJs; we examined the expression of TJ proteins including ZO-1, claudin-1, and occludin using immunofluorescence assay in DSS-induced colitis mouse colon tissue." (PMID 33233771, 2020). "In the DSS-induced colitis group, there were substantial reductions in zonula occludens-1 (ZO-1) and occludin mRNA levels; however, these recovered to the control levels in the low-dose IL-2 groups (16K IU/day and 32K IU/day)." (PMID 32308767, 2020). "Others have previously demonstrated the direct and protective role of IL-17C in regulating occludin production by colonic epithelial cells in mice during acute experimental colitis." (PMID 31221216, 2019). "On the basis of that observation, it is conceivable that PWS can improve paracellular permeability as well as epithelial barrier function in DSS + CD-induced colitis by upregulating occludin and claudin-1 expressions." (PMID 31888274, 2019). "Our results showed that GABA and muscimol decreased JAM-1 and occludin expression on day 3 in the DSS-induced colitis mouse model, an effect which was blocked by bicuculline." (PMID 29867964, 2018). "Further study of this issue indicated that GABA and muscimol reduced JAM-1 and occludin expression in colitis mice." (PMID 29867964, 2018). "In the present study, DSS-induced colitis was also associated with a reduction in the expression of mucins, MUC-2 and MUC-3, and tight junction proteins, OCLN and ZO-1, which participate in maintaining epithelial integrity." (PMID 29867475, 2018). "We found that metformin protected against loss of the TJ proteins occludin and ZO‐1, decreases in TEER, FD4 hyperpermeability and bacterial translocation in Caco‐2 cell monolayers or in DSS‐induced colitis mice." (PMID 29148173, 2018). "In contrast, the gut epithelial cells in the DSS-induced colitis group exhibited diffused occludin staining that appeared to extend into cytoplasm as compared to the control group." (PMID 29375374, 2017). "In this study, we show that the genetic or pharmacological inhibition of PLD2 restored occludin levels, alleviated the symptoms of colitis, and improved the survival rate of the mice." (PMID 28484281, 2017). "In another study, naringenin ameliorated DSS-induced colitis by restoring the expression of tight junction proteins such as occludin, junctional adhesion molecule-A, and claudin-3." (PMID 27635116, 2016). "Compared with control group, the expression of tight junction associated proteins including ZO-1, E-cadherin, and occludin, was decreased in DSS-induced colitis mice, indicating that intestinal barrier function was damaged seriously." (PMID 27574508, 2016). "Importantly, CPE was able to recover ZO-1 and occludin localization to apical junction and suppressed tight junction-dependent leak pathway permeability in colitis mice." (PMID 42163411, 2026). "Furthermore, EGT ameliorated DSS-induced colitis, reducing macrophage infiltration and restoring the expression of tight junction proteins ZO-1, Occludin and MUC2, confirming its broad anti-inflammatory and barrier-protective activities." (PMID 41530565, 2026). "Moreover, PA improved intestinal barrier damage in mice with DSS-induced experimental colitis by increasing the expression levels of ZO-1 and occludin." (PMID 40969742, 2025).
colitis (continued). "Moreover, the levels of phosphorylated p38 and phosphorylated ERK decreased, and the expression of ZO‐1 and Occludin increased in colitis tissues in the F. nucleatum+DSS+IFX+FK866 group." (PMID 39739648, 2025). "In a colitis rat model, oral administration of baicalin (100 mg/kg) could enhance mRNA expression levels of ZO-1 and occludin, ameliorating TNBS-induced colitis (Zhu, Xu, Zhao, Shen, Shen and Zhan, 2020)." (PMID 41145081, 2025). "In conclusion, we demonstrate that the culture supernatant of A.m alleviated colitis in IL-10−/− mice by suppressing pro-inflammatory cytokines, enhancing anti-inflammatory mediators, and upregulating epithelial tight junction proteins ZO-1 and occludin." (PMID 41333470, 2025). "An oral 5-ASA delivery system has demonstrated significant alleviating effects in a DSS-induced colitis model, upregulating the expression of claudin-1, Occludin, and zonula occludens-1 (ZO-1) in NCM460 cells and enhancing intestinal epithelial barrier integrity." (PMID 41140699, 2025). "S1P alleviated DSS-induced colitis by suppressing inflammatory cell infiltration, reducing ulcers, and maintaining intestinal epithelial junction integrity by increasing E-cadherin and occludin expression." (PMID 40761802, 2025). "Furthermore, the protein expression of E‐cadherin and Occludin was down‐regulated in DSS‐induced colitis mice; whereas these effects were reversed by UMSCs, suggesting that UMSC therapy protects the mucosal barrier." (PMID 40842289, 2025). "In DSS-induced colitis, LR restores the expression of TJ proteins (ZO-1, Occludin, Claudin-3)." (PMID 41403703, 2025). "The synbiotic FCT (fermented milk with L. gasseri 505 and C. tricuspidata) has demonstrated concurrent upregulation of MUC2, TFF3, and tight junction proteins (occludin, ZO-1), along with significant downregulation of TNF-α, IFN-γ, IL-1β, IL-6, and iNOS/COX-2 in colitis-associated cancer models." (PMID 41395459, 2025). "Similarly, we also found that the expression of ZO-1 and Occludin was reversed by SC in colitis mice." (PMID 39936162, 2025). "Our study showed that the expression of ZO1 and claudin-1 at both mRNA and protein levels and the expression of occludin at mRNA level were significantly reduced in DSS-induced colitis mice, but they were significantly increased in A. shahii As360-treated colitis mice." (PMID 39936902, 2025). "Moreover, HFCD intake has been associated with intestinal barrier alterations through the downregulation of tight junction proteins (occludin, ZO-1, and claudin-4) and gut dysbiosis, which exacerbate gastrointestinal symptoms in colitis models." (PMID 41425635, 2025). "Tong and others found that bovine and human milk-derived EVs could upregulate the expression levels of Muc2, ZO-1, and Occludin to improve intestinal barrier function and reduce colitis in mice." (PMID 40361597, 2025). "However, GSK-J4 alleviated DSS-induced and YAPIEC−/−-aggravated acute colitis by suppressing the proinflammatory response with reduced levels of chemokines and ameliorating intestinal injury by reversing Occludin and E-cadherin expression." (PMID 38245781, 2024). "Furthermore, LM-CsA NPs significantly decreased the expression of inflammatory factors such as TNF-α and IL-6 and increased the expression of gut barrier-related proteins such as E-cadherin, ZO-1, and occludin protein in colitis mice." (PMID 39512421, 2024). "To comprehensively investigate the extent of intestinal barrier damage in DSS-induced colitis mice and the effects of heat-killed S. boulardii on the intestinal barrier, we used Western blots to measure the levels of tight junction proteins Occludin and ZO-1 in the colon." (PMID 38474831, 2024). "This study found that both LWB and HWB could alleviate the reduced mRNA expression levels of tight junction proteins (ZO-1, Claudin-1, and Occludin) present in the colonic tissue of mice induced with colitis." (PMID 38254526, 2024).